HINT1 (histidine triad nucleotide binding protein 1)
Diseases named in the same sentence as HINT1 in open-access papers (continued):
Sharing a sentence is not in itself a finding about the gene and the disease.
neuropathy (12 papers, 2015 to 2026). A disorder affecting the nervous system that manifests with pain, tingling, numbness, and/or muscle weakness. "This comparative case study of DNAJB2‐ and HINT1‐related neuropathies aimed to broaden the phenotypic spectrum associated with these genes and to explore non‐motor symptoms and quality of life (QoL) in affected individuals." (PMID 41549766, 2026). "Overall, the genetic epidemiology suggests that HINT1 neuropathy should be considered in the diagnostic work-up of patients of European descent presenting with axonal CMT." (PMID 36873433, 2023). "With 25 causal variants identified worldwide, HINT1 mutations are among the most common causes of recessive neuropathy." (PMID 36242072, 2022). "Although the causal association between pain and HINT1 neuropathy is uncertain, studies in HINT1 KO mice showed a link with nociception and demonstrated a modulatory effect on the cannabinoid pathway." (PMID 33663550, 2021). "This study represents the first analysis of HINT1 neuropathy in Norway, where we identified a rare novel allele (p.Arg95Gln) and investigated the frequency of the most common HINT1 allele (p.Arg37Pro) in a large population sample from Norway." (PMID 33663550, 2021). "The volcano plot highlighted significant up- and down-regulated genes between WT and HINT1-KO cells, with the up-regulated genes being primarily involved in neural development, potentially linked to HINT1 gene polymorphisms in human behaviors and neuropathy." (PMID 40695554, 2025). "Notably, most of the variants causing HINT1 neuropathy occur at a low frequency and, similarly to this report, often patients are compound heterozygous." (PMID 33663550, 2021). "Thus, NR1 C1 and the neuropathy-related NR2B subunit increase two-fold in 129 HINT1−/− mice, and α2δ1 proteins increase their association with these subunits, which influences NMDAR activity." (PMID 34827679, 2021). "This study expands the clinical spectrum of DNAJB2‐ and HINT1‐related neuropathies, highlighting distinct non‐motor features and their impact on QoL, and providing the first direct comparison of these two rare axonal disorders." (PMID 41549766, 2026). "The identification of pathogenic variants in well-established neuropathy-associated genes such as PMP22, MME, MPV17, and HINT1 confirms the value of CES, particularly when traditional single-gene screening is inconclusive." (PMID 41509941, 2025). "Our findings broaden the phenotype of HINT1-neuropathy and have implications for diagnostics and ultrasonographic evaluation of HINT1-neuropathy patients." (PMID 36873433, 2023). "Here, we performed the first systematic assessment of HINT1 neuropathy in Lithuania and describe a potential new founder event in the Baltic region." (PMID 36242072, 2022). "Our findings broaden the genetic epidemiology of HINT1-neuropathy and have implications for molecular diagnostics of inherited peripheral neuropathies in Scandinavia." (PMID 33663550, 2021). "In Czechia and Russia, HINT1-neuropathy ranks among the most frequent forms of axonal neuropathy while in Bulgaria cases of pseudo-dominant inheritance have been identified (A. Jordanova, unpublished data)." (PMID 33663550, 2021). "On morphine clearance, HINT1 again falls under the control of the MOR, although in neuropathies the transfer of HINT1 predominates until the influence of the activated GPCRs vanishes." (PMID 26461475, 2015). "Disease onset was typically later in patients with DNAJB2 variants (late adolescence or early adulthood) compared to patients with HINT1 variants (childhood or early adolescence), yet patients with DNAJB2 variants more frequently developed severe neuropathy, as reflected by higher CMTNS scores." (PMID 41549766, 2026). "Both groups of patients with DNAJB2‐ and HINT1 neuropathy exhibited a CMT2 phenotype." (PMID 41549766, 2026).
neuropathy (continued). "This is the first report of HINT1-neuropathy in Northern Europe." (PMID 33663550, 2021). "Thus, our study reports the presence of such neuropathy-related α2δ1-NMDAR associations at the supraspinal PAG level that depend on the interplay between σ1Rs and HINT1 proteins." (PMID 34827679, 2021). "In HINT1‐related neuropathy, hearing loss has not been reported to date." (PMID 41549766, 2026). "Animal models with complete HINT1 insufficiency have been developed, and none of them have a neuropathy phenotype." (PMID 36873433, 2023). "Notably, mice with a targeted deletion of the sigma 1 receptor (σ1R) gene do not develop neuropathy, whereas mice lacking the histidine triad nucleotide-binding protein 1 (Hint1) gene exhibit exacerbated allodynia." (PMID 34827679, 2021). "Interestingly, targeted disruption of the HINT1 gene does not promote neuropathy-related phenotypes, at least in mice." (PMID 31088288, 2019). "The HINT1 protein reduces the formation of pro-allodynic (α2)δ1-σ1R-NMDAR complexes and thus, neuropathy is enhanced in the absence of HINT1." (PMID 34827679, 2021).
Anxiety (11 papers, 2009 to 2025). Intense feelings of nervousness, tension, or panic often arise in response to interpersonal stresses. "Although HINT1 KO mice exhibit normal fetal and adult development, they show increased susceptibility to tumor formation and display increased anxiety-like behavior along with impaired motor coordination." (PMID 40695554, 2025). "Our study investigated the relationships between cigarette smoking, personality traits, anxiety, and the rs2526303 polymorphism within the HINT1 gene." (PMID 38279213, 2024). "The EPM test was applied to detect anxiety‐related behavior in mice with complete or partial loss of Hint1 under basal or CIS conditions." (PMID 29075577, 2017). "Additionally, we investigated the associations between personality traits, anxiety, and the rs2526303 polymorphism in the HINT1 gene." (PMID 38279213, 2024). "However, the phenotypes of antidepressant-like and less anxiety-related behaviors were associated with increased corticosterone levels in PKCI/HINT1 KO mice." (PMID 19912621, 2009). "The finding of a trend toward anxiolytic‐like effects in the elevated anxiety‐like behavior in Hint1‐KO mice after CIS indicates that CIS plays an important role in changes in anxiety‐related behaviors, and that the underlying mechanism may involve activation of the HPA axis by stress." (PMID 29075577, 2017). "Possible influences on anxiety levels are still under investigation since the pertinent literature shows evidence for reduced or elevated levels of anxiety in HINT1-KO mice." (PMID 39596683, 2024). "The studies provide evidence supporting the potential involvement of the HINT1 gene in plasticity, mood regulation, anxiety-like behaviour, and stress-coping mechanisms." (PMID 39062900, 2024). "Studies conducted on HINT1 knocked-out (KO) mice showed a reduction in social behaviors and an increase in anxiety-related behaviors, aggressiveness, and schizophrenic traits, suggesting a significant role of this gene in the regulation of mood and behavior." (PMID 39596683, 2024). "Recent research has suggested the potential involvement of the HINT1 gene in various aspects of plasticity, mood regulation, anxiety-like behaviour, and stress-coping mechanisms." (PMID 38279213, 2024). "In human patients with SCZ, histidine triad nucleotide-binding protein 1 is associated with acute behavioural changes, whereas histidine triad nucleotide-binding protein 1 knockout mice show elevated anxiety- and depression-like behaviours." (PMID 30809121, 2019). "After CIS, Hint1‐HT mice showed elevated anxiety‐related behavior and increased depression‐like behavior, while Hint1‐KO mice displayed elevated anxiety‐related behavior and reduced depression‐like behavior." (PMID 29075577, 2017). "Taken together, these results showed that both male and female Hint1‐KO and ‐HT mice demonstrated elevated anxiety‐related behavior under CIS." (PMID 29075577, 2017). "They concluded that HINT1 KO mice exhibited increased anxiety-like behavior compared with that in WT mice." (PMID 29214080, 2017). "We also looked at the involvement of PKCI/HINT1 in the light/dark paradigm and in thigmotaxis as indices of anxiety-related behavior, and we used the Morris water maze test for place navigation learning to assess goal-oriented behavior." (PMID 19912621, 2009). "We submitted PKCI/HINT1 KO mice and their wild type (WT) littermates to behavioral tests used to study anti-depressant, anxiety like behaviors, and goal-oriented behavior." (PMID 19912621, 2009). "In our studies regarding HINT1 variants and personality traits, we did not observe interactions regarding anxiety as a trait or as a state, nor neuroticism, which is related to anxiety." (PMID 39062900, 2024).
Anxiety (continued). "Varadarajulua reported that Hint1‐KO mice demonstrated increased anxiety‐related behavior and elevated emotional‐like arousal, as compared with WT mice, while the findings of Wang revealed that deletion of Hint1 in mice demonstrated anxiolytic‐like and antidepressant‐like effects." (PMID 29075577, 2017). "Indeed, CB1R−/− mice exhibit depressive-like and anxiety-like behaviors in several behavioral paradigms, and in our study, the HINT1 and NR1 C1 subunit levels increased in these mice." (PMID 29249810, 2017). "However, Varadarajulu and colleagues have reported that Hint1‐KO mice showed increased anxiety‐like behavior." (PMID 29075577, 2017). "These statistical results of EPM revealed that there were no significant gender differences on anxiety‐related behavior in mice with Hint1 deficiency under basal or CIS conditions." (PMID 29075577, 2017). "Additionally, PKCI/HINT1 KO mice in the Morris water maze place navigation task displayed significantly less thigmotaxis than the WT mice, showing less anxiety behavior related to open space." (PMID 19912621, 2009). "Moreover, studies utilising HINT1 knockout mice have indicated that HINT1 may be involved in the aetiology of antidepressant and anxiety-like behaviours." (PMID 39062900, 2024). "In addition, studies using HINT1 knockout mice suggest that HINT1 may play a role in antidepressant and anxiety-like behaviours." (PMID 38279213, 2024). "Thus some of the results implicated here may imply that there is accelerated habituation in PKCI/HINT1 KO mice, at least to the anxiety-provoking aspects of the experimental environments." (PMID 19912621, 2009). "However, both male and female Hint1‐KO mice showed increased anxiety‐related behavior but antidepressant‐like behaviors under CIS; moreover, both male and female Hint1‐HT mice displayed elevated anxiety‐related behavior and increased depression‐like behavior under CIS." (PMID 29075577, 2017).
depression (11 papers, 2017 to 2026). "All patients with DNAJB2 variants met criteria for depression, while only one patient with HINT1 variants had depression (P4)." (PMID 41549766, 2026). "All patients with DNAJB2 variants fulfilled criteria for depression, compared with one with a HINT1 variant." (PMID 41549766, 2026). "It has already been demonstrated that an alteration of mRNA/HINT1 expression occurs in post-mortem brains of patients with mood disorders, specifically in those with a diagnosis of bipolar disorder and major depressive disorder." (PMID 39596683, 2024). "The present study utilized a rat model exposed to chronic mild stress (CMS) to explore the involvement of HINT1 in depression." (PMID 34177485, 2021). "In support of using HINT1−/− mice as a model for human BPD, MK801 and, to a lesser extent, citalopram by reducing depression-like behaviors increased the activity of HINT1+/+ WT mice and rescued the manic-like state in stressed HINT1−/− mice." (PMID 28240305, 2017). "It still remains elusive that how HINT1 involves in depression." (PMID 34177485, 2021). "The results suggest that the suppression of HINT1 might have potential as a novel therapeutic strategy for depression." (PMID 34177485, 2021). "However, Hint1‐HT mice increased depression‐like behavior after CIS, while Hint1 knockout in female mice tended to have antidepression‐like effects." (PMID 29075577, 2017). "Moreover, in a study using the chronic mild stress (CMS) depression model to explore the antidepressant effect of oleamide, proteomics analysis showed that the expression level of HINT1 protein in the hippocampus of the CMS group was increased." (PMID 29214080, 2017). "However, there are few studies reported the relationship between HINT1 and OS/ROS in depression." (PMID 34177485, 2021). "The immobility time of Hint1‐KO and ‐HT mice and their WT littermates in the TST was used to measure the depression‐like behavior." (PMID 29075577, 2017).
axonal neuropathy (8 papers, 2016 to 2026). Any nerve disorder affecting the axon of a nerve. "In conclusion, we expand the clinical spectrum of DNAJB2‐ and HINT1‐related hereditary neuropathies, describing the phenotype beyond motor symptoms and providing a direct comparison of these two rare axonal neuropathies." (PMID 41549766, 2026). "The HINT1 gene is especially prevalent in eastern Europe (Czech Republic); its clinical presentation is that of an axonal neuropathy accompanied by neuromyotony." (PMID 34438578, 2021).
melanoma (7 papers, 2019 to 2025). A malignant, usually aggressive tumor composed of atypical, neoplastic melanocytes. "Mutant colon cancer and melanoma cell lines with completely deacetylated HINT1 showed significantly reduced growth." (PMID 32636443, 2020). "A crucial modification to the tumor-suppressing gene HINT1 helps slow the spread of colon cancer and melanoma according to researchers in South Korea." (PMID 32636443, 2020). "In support of this, the deacetylation mimetic HINT1 mutant HINT1 2KR was found to significantly reduce cellular proliferation in colon cancer and melanoma cells and tumorigenesis in xenograft assays." (PMID 32636443, 2020). "Previously, many studies have suggested that HINT1 can serve as a novel tumor suppressor in various types of cancer, such as melanoma, gastric cancer, and colon cancer, and may also have an important role in the treatment of neuropsychiatric diseases." (PMID 32636443, 2020). "The dissociation of the HINT1-MITF complex can also be induced in melanoma cells through post-translational modification of HINT1 residues surrounding the MITF-HINT1 interface, which may allow prolongation of MITF-controlled processes." (PMID 33282915, 2020). "Indeed, ectopic expression of the HINT1 2KR (K21/30R) mutant mimicking deacetylation status in colon cancer or melanoma cells significantly suppresses the growth and viability of those cells compared to those of wild-type HINT1." (PMID 32636443, 2020). "The regulation of HINT1-MITF is also found in melanoma cells." (PMID 31604935, 2019). "In colon cancer and melanoma cells, deacetylation by SIRT1 promotes tumor suppressor activity by enhancing the ability of histidine triad nucleotide-binding protein 1 (HINT1) to bind to β-catenin or MITF, resulting in an increase in the tumor suppressor function of HINT1123." (PMID 39479446, 2024). "In conclusion, this study demonstrates that reversible acetylation of HINT1 at K21 and K30 by CBP and SIRT1 modulates the capacity of HINT1 to bind to β-catenin or MITF and in turn to control tumorigenic features in colon cancer and melanoma cells." (PMID 32636443, 2020). "Thus, we further explored whether reversible acetylation of HINT1 could affect the interaction of HINT1 with MITF and then affect MITF-mediated oncogenic function in the A375 melanoma cell line." (PMID 32636443, 2020). "Similar to β-catenin, previous studies demonstrated that HINT1 could also interact with and repress the function of MITF, which has been well known as a master regulator of melanocyte development and function, in activated mast and melanoma cells." (PMID 32636443, 2020).
colon cancer (5 papers, 2020 to 2024). "After transfection of the HINT1 WT or 2KR construct into the A375 colon cancer cell line, the association of HINT1 with MITF and the endogenous expression levels of MITF target genes, including tyrosinase and CDK2, were investigated." (PMID 32636443, 2020). "The A375 colon cancer cells were stably transfected with lentiviral vectors expressing either HINT1 WT or HINT1 2KR, and then the cell proliferation rate and cell viability were examined." (PMID 32636443, 2020). "This study assessed the ability of colon cancer cells, which were stably transfected with the HINT1 WT or 2KR construct, to proliferate, form colonies, and survive." (PMID 32636443, 2020). "However, we confirmed that HINT1 is a tumor suppressor gene in colon cancer cells and there are still some limitations in our study." (PMID 33123275, 2020). "Additionally, histidine triad nucleotide-binding protein 1-Profilin1, a key molecule in actin cytoskeletal remodeling, was downregulated as well; this impact of Polyphyllins could deter colon cancer cell’s invasion ability." (PMID 35327385, 2022). "After transient transfection with Hint1 by plasmids, human SW480 colon cancer cells and human MCF-7 breast carcinoma cells underwent apoptosis as analyzed by the expression of pro-caspase-3 and poly (ADP-ribose) polymerase cleavage." (PMID 34177485, 2021). "Likewise, overexpression of the HINT1 2KR mutant also significantly diminished cell viability and the number of colonies formed when compared with the results for HINT1 WT, indicating that HINT1 deacetylation promotes its tumor-suppressive function in the colon cancer cell lines DLD1 and SW480." (PMID 32636443, 2020). "Moreover, HINT1 deacetylation by SIRT1 promotes the association of HINT1 with β-catenin, thus inhibiting carcinogenesis through downregulating β-catenin oncogenic activity, which suggests that SIRT1 might serve as a tumor suppressor through deacetylation of HINT1 and β-catenin in colon cancer cells." (PMID 32636443, 2020).
hepatocellular carcinoma (5 papers, 2013 to 2025). A malignant tumor that arises from hepatocytes. "Downregulated Hint1 expression was found in metastatic lymph nodes cells in hepatocellular carcinoma, involving Hint1 in a migration and invasion process by modulating girdin and AKT expression and phosphorylation." (PMID 33671384, 2021). "Our previous study showed that HINT1 functions as a tumor-suppressor gene in human hepatoma cell lines." (PMID 24396396, 2014). "In a hepatoma cell line, HINT1 inhibits activity of Wnt/ß-catenin signaling and gene transcription via TCF4." (PMID 24386364, 2013).
cardiac hypertrophy (4 papers, 2023 to 2025). "Furthermore, Hint1 has been implicated in cardiovascular diseases like cardiac hypertrophy." (PMID 38068718, 2023). "Our previous study identified the role of HINT1 in cardiovascular diseases, in which HINT1 in cardiomyocytes protects from cardiac hypertrophy as an important signal transduction player in cytoplasm." (PMID 40198125, 2025).
diabetes (4 papers, 2019 to 2023). "Employing an animal model of limb ischemia under the background of STZ-induced diabetes mellitus, we thoroughly examine the impact of Hint1 deficiency and endothelium-specific Hint1 overexpression on blood perfusion and capillary formation in mice." (PMID 38068718, 2023). "To examine the impact of Hint1 on blood flow recovery in chronic ischemic injury related to diabetes, we employed a mouse model of lower limb ischemia, using both Hint1-knockout (KO) and wild-type (WT) mice." (PMID 38068718, 2023). "The downregulation of HINT1 has also been reported in diabetes and AD." (PMID 36195955, 2022).